STRIP1 (striatin interacting protein 1)
Description:
Plays a role in the regulation of cell morphology and cytoskeletal organization. Required in the cortical actin filament dynamics and cell shape. Part of the striatin-interacting phosphatase and kinase (STRIPAK) complexes. STRIPAK complexes have critical roles in protein (de)phosphorylation and are regulators of multiple signaling pathways including Hippo, MAPK, nuclear receptor and cytoskeleton remodeling. Different types of STRIPAK complexes are involved in a variety of biological processes such as cell growth, differentiation, apoptosis, metabolism and immune regulation.
Synonyms: FAM40A; KIAA1761; FLJ14743; FAR11A
Tractability: PROTAC: ubiquitination databases record sites on it; its protein half-life has been measured.
Gene: Protein-coding gene on chromosome 1 (110,031,577 to 110,074,641, forward strand). Ensembl gene ENSG00000143093.
Subcellular location: Cytoplasm
Subcellular location (Human Protein Atlas): Cytosol
Gene Ontology:
Molecular function: protein binding; protein-macromolecule adaptor activity; protein kinase binding; small GTPase binding
Biological process: negative regulation of hippo signaling; cytoskeleton organization; regulation of hippo signaling
Cellular component: cytosol; extracellular exosome; FAR/SIN/STRIPAK complex; nucleus; cytoplasm
Genetic constraint (gnomAD): Loss-of-function variants: 60 observed, 95.07 expected, observed/expected ratio (o/e) 0.63, 90% interval 0.51 to 0.78. The upper end of that interval is the gene's LOEUF score, 0.78, which puts it in group 3 of 6, group 1 being the genes least tolerant of losing a copy. Missense variants: 817 observed, 1,025.1 expected, observed/expected ratio (o/e) 0.8, 90% interval 0.75 to 0.84. Synonymous variants: 377 observed, 392.92 expected, observed/expected ratio (o/e) 0.96, 90% interval 0.88 to 1.04.
Homologues: Orthologues: chimpanzee STRIP1 (100% identical), dog STRIP1 (99% identical), pig STRIP1 (99% identical), rabbit STRIP1 (99% identical), guinea pig STRIP1 (98% identical), mouse Strip1 (98% identical), rat Strip1 (98% identical), macaque STRIP1 (97% identical), tropical clawed frog strip1 (86% identical), zebrafish strip1 (84% identical), Drosophila melanogaster Strip (51% identical), Caenorhabditis elegans farl-11 (40% identical). Paralogues in human: STRIP2 (69% identical).
Diseases named in the same sentence as STRIP1 in open-access papers:
STRIP1 is named in the same sentence as 13 diseases in open-access papers, as found by Europe PMC text mining. Sharing a sentence is not in itself a finding about the gene and the disease. The quoted sentences say what the papers report.
breast carcinoma (4 papers, 2018 to 2023). "In this study, we demonstrate that loss of STRIP1 in breast cancer cells also induces p21 and p27 expression in a MST3&4 dependent manner." (PMID 32258031, 2020). "From a mechanistic perspective, we demonstrate that loss of STRIP1 impedes the cell cycle progression and proliferation of breast cancer cells by inducing expression of p21 and p27, two bonafide CDK inhibitors and G1 checkpoint regulators." (PMID 32258031, 2020). "Although a lower level of STRIP1 was shown to supress breast cancer cell proliferation via interference with cell cycle regulation, decreased STRIP1 exhibited tumour-promoting effects when cells were treated with a non-lethal dose of doxorubicin or cisplatin." (PMID 38201504, 2023). "In conclusion, our findings suggest that STRIP1 antagonizes the two MST3&4 kinases in breast cancer cells." (PMID 32258031, 2020). "We demonstrated that loss of STRIP1 induces strong activation of the two MST3&4 kinases, consequently inducing breast cancer cells to metastasize using actomyosin-driven amoeboid migration." (PMID 32258031, 2020). "Isoform 2 of STRIP2 has been proposed to antagonize the function of STRIP1 to promote breast cancer metastasis." (PMID 30622739, 2019). "Additionally, the activation of MST3/4, which can be antagonised by the presence of STRNs and STRIP1 in breast cancer cells, was shown to facilitate cell migration by activating ERM proteins and inhibiting myosin light chain dephosphorylation." (PMID 38201504, 2023). "Interestingly, although STRIP1 depletion has a tumour-suppressive role in breast cancer proliferation via communication with P21 and P27, it showed a contradictory characteristic upon the administration of chemotherapies to cells." (PMID 38201504, 2023). "This corroborates with already known research on the dual role of p21 and indicates that STRIP1 also plays a contradictory role in breast cancer, suppressing tumor growth, but once treated with chemotherapeutics, allowing for possible recurrence and decreased patient survival." (PMID 32258031, 2020). "Although these Kaplan Meier analyses are inconclusive due to low patient numbers, they do support the notion that STRIP1 may play an important role in breast cancer." (PMID 32258031, 2020). "In conclusion, our observations demonstrate a conflicting function of STRIP1 in regulating proliferation of breast cancer; low levels of STRIP1 suppress proliferation of untreated cells while inducing proliferation of cells recovering from non-lethal doses of chemotherapy." (PMID 32258031, 2020). "With the involvement of STRIPAK in cell cycle control, the breast cancer cell line MDA-MB-231 exhibited cell cycle arrest and suppressed cell proliferation and growth upon depletion of STRIP1." (PMID 38201504, 2023). "In this paper, we continue to elaborate on the molecular and biological functions of STRIP1 and MST3&4 in breast cancer." (PMID 32258031, 2020). "GCKIII kinases MST3/4 can phosphorylate PPP1R14A-D to advance breast cancer metastasis via modulating the actomyosin cytoskeleton, while STRN3/4, STRIP1, and PP2A suppress the activity and function of MST3/433." (PMID 30622739, 2019).
cardiomyopathy (1 paper, 2026). A disease of the heart muscle or myocardium proper. "Collectively, these findings establish Strip1 as an important modulator of cardiomyocyte hypertrophy and a potential therapeutic target for cardiomyopathy and heart failure." (PMID 41892331, 2026).
dilated and (1 paper, 2026). "STRIP1 expression was found to be significantly reduced in human dilated and ischemic cardiomyopathies (DCM/ICM), as well as in murine stress model induced by transverse aortic constriction (TAC)." (PMID 41892331, 2026).
glaucoma (1 paper, 2022). Increased pressure in the eyeball due to obstruction of the outflow of aqueous humor. "Moreover, this study paves the way for future research investigating Strip1 as a potential therapeutic target to slow down the death of RGCs in conditions such as glaucoma." (PMID 35314028, 2022).
heart failure (1 paper, 2026). Inability of the heart to pump blood at an adequate rate to meet tissue metabolic requirements. "In a knockdown model with morpholino-driven STRIP1 reduction in zebrafish in vivo, impaired cardiac function and heart failure-like features were observed." (PMID 41892331, 2026).
type 2 diabetes (1 paper, 2021). "Striatin-interacting protein 1 (Strip1) is a core component of the striatin interacting phosphatase and kinase (STRIPAK) complex, which is involved in embryogenesis and development, circadian rhythms, type 2 diabetes, and cancer progression." (PMID 33889175, 2021).
cancer (9 papers, 2015 to 2024). A tumor composed of atypical neoplastic, often pleomorphic cells that invade other tissues. "Strip1 is also involved in cancer cell migration and metastasis, and loss of Strip1 results in cell cycle arrest and subsequent reduced tumor growth by inducing the expression of cyclin-dependent kinase inhibitors." (PMID 33889175, 2021). "MAP4K4 was shown to be involved with FA disassembly; STRIP1 deficient MEFs exhibited reduced number of FA with increase in their clustering; and depletion of CCM3 in cancer-associated fibroblasts increased the size and number of FA per cell." (PMID 39417621, 2024). "In Omy17, we found the striatin-interacting protein one homolog (STRIP1) gene, which plays an important role in the migration and metastasis of cancer cells and regulates the organization of the actin cytoskeleton." (PMID 36672855, 2022). "Here, we expand on previous work indicating a role for the scaffolding protein STRIP1 in cancer cell migration and metastasis." (PMID 32258031, 2020). "On the contrary, low STRIP1 levels would have a poor prognosis in patients receiving chemotherapy, due to recovery and recurrence of treated cancer cells." (PMID 32258031, 2020). "For example, Strip1 and 2, homologs of Drosophila Strip, were recently identified as regulators of the actomyosin contraction that regulates cell migration in cancer cells." (PMID 26644129, 2015). "In cancer cells, STRIP1, STRIP2, and STRN3 regulate cell migration and metastasis by negatively influencing MST3 and MST4 kinases, which act through the ezrin-radixin-moesin family proteins to promote the actomyosin machinery by phosphorylating PP1 and PPP1R14A-D." (PMID 38999976, 2024). "STRIP1 also functions as a negative regulator for GCKIII members in cancer cells." (PMID 38201504, 2023). "STRIP1, STRIP2, and STRN3 have been identified as regulators of actomyosin, while MST3 and MST4, members of GCKIII kinases, regulate cancer cells migration." (PMID 38999976, 2024). "Another recent study demonstrated the interaction of STRIP1/2 with CCM3 in endothelial cells, collectively regulating blood-brain barrier integrity, which is crucial for cancer-induced brain metastasis." (PMID 38201504, 2023). "In our previous work, we demonstrated that STRIP1 is a negative regulator of MST3 and MST4 in cancer cells." (PMID 32258031, 2020).
tumor (6 papers, 2020 to 2023). "While the loss of STRIP1 decreases cell proliferation and tumor growth, cells treated with low dosage of chemotherapeutics in vitro paradoxically escape therapy-induced senescence and begin to proliferate after recovery." (PMID 32258031, 2020). "We show that loss of STRIP1 induces the expression of cyclin dependent kinase inhibitors (CKI) including CDKN1A (p21), which leads to cell cycle arrest and reduced tumor growth." (PMID 32258031, 2020). "However, depletion of STRIP1 increases the MAP4K4 activation signature and the invasive potential of tumor cells, suggesting a negative regulatory role of STRIP1, possibly by making MAP4K4 accessible to PP2A." (PMID 36568222, 2022). "From a speculative perspective, these observations suggest that low levels of STRIP1 may correlate with good prognosis in untreated patients, due to lower tumor growth." (PMID 32258031, 2020). "However, the lack of a clear phenotype after STRIP1 depletion also indicates only a minor contribution to migration and growth control in MB tumor cells." (PMID 35941177, 2022).
infection (1 paper, 2024). The state of being infected such as from the introduction of a foreign agent such as serum, vaccine, antigenic substance or organism. "Only three proteins (GSN, PLEC, and STRIP1) and one transcript (MYOM3) related to the cytoskeleton organization and dynamics were regulated in the lower trachea after infection with huH1N1." (PMID 39247193, 2024).
STRIP1 also shares sentences with these, for which no sentence is quoted: cerebral cavernous malformation (1 paper); ischemic cardiomyopathies (1); optic neuropathies (1); psychosis (1).